APOE (apolipoprotein E)
Diseases named in the same sentence as APOE in open-access papers (continued):
Sharing a sentence is not in itself a finding about the gene and the disease.
lipoprotein glomerulopathy (27 papers, 2009 to 2025). "Lipoprotein glomerulopathy (LPG) is a apolipoprotein E (ApoE)-related glomerular disease and has been associated with type III hyperlipidemia." (PMID 38769490, 2024). "Lipoprotein glomerulopathy (LPG) is an inherited glomerular disease caused by mutations in the APOE gene, usually with clinical manifestations of dysregulated lipid metabolism, proteinuria, and renal insufficiency." (PMID 38448817, 2024). "Lipoprotein glomerulopathy (LPG) is a rare autosomal dominant kidney disease caused by pathogenic mutations in the APOE gene." (PMID 36370330, 2023). "Due to space limitations, we will not review the role of apoE in health and disease of the kidney, including the relationship between minor apoE variants and glomerulopathy." (PMID 36077289, 2022). "Here we report two cases of lipoprotein glomerulopathy, a Chinese son and his father, with a novel apolipoprotein E mutation, ApoE Ganzhou (Arg43Cys)." (PMID 35193676, 2022). "Apolipoprotein E-related glomerular disorders include APOE2 homozygote glomerulopathy and LPG with heterozygous APOE mutations." (PMID 35602473, 2022). "Since the discovery of lipoprotein glomerulopathy, 16 different apolipoprotein E mutations have been reported worldwide, but most of these cases are sporadic." (PMID 35193676, 2022). "We report two unrelated cases of Brazilian patients with a diagnosis of lipoprotein glomerulopathy whose genetic assessment identified the APOE-Osaka/Kurashiki pathogenic variant, previously only described in eastern Asians." (PMID 34311745, 2021). "Lipoprotein glomerulopathy (LPG) is a rare autosomal dominant kidney disease that is most commonly caused by mutations in ApoE Kyoto (p.R43C) and ApoE Sendai (p.R163P)." (PMID 33663537, 2021). "Lipoprotein glomerulopathy (LPG) is a rare kidney disease with a poor prognosis that is related to mutation of the apoE gene." (PMID 31092271, 2019). "Other mouse models in which lipoprotein glomerulopathies are described include virus-mediated transduction of the apoE Sendai mutation in apoE-deficient mice and aged apoE-deficient mice." (PMID 25353171, 2014). "Variants of apolipoprotein E have been linked to lipoprotein glomerulopathy (LPG), a glomerular disease characterized by the deposition of lipoproteins in glomerular capillaries." (PMID 20727187, 2010). "The phenotypic expression of lipoprotein glomerulopathy is most probably correlated to a genetic alteration of the lipoprotein metabolism (mutation of the Apolipoprotein E coding gene)." (PMID 20062740, 2009). "The location of the gene mutation is close to the most common mutation type of lipoprotein glomerulopathy, ApoE Kyoto (Arg25Cys), so we speculate that its pathogenic role might be the similar to that of ApoE Kyoto (Arg25Cys)." (PMID 35193676, 2022). "Hepatic gene expression of Esrrg was upregulated 2.4-fold in a study on candidate genes that affect lipid and lipoprotein metabolism in response to fenofibrate treatment, interestingly the same treatment induced remission of lipoprotein glomerulopathy in patients with the apoE Kyoto mutation." (PMID 25353171, 2014). "This article reports an extremely rare case of lipoprotein glomerulopathy (LPG) with apolipoprotein E gene (APOE) Chicago mutation in a young Chinese male." (PMID 38448817, 2024). "Lipoprotein glomerulopathy (LPG) is a rare autosomal dominant disease caused by mutations in APOE, the gene which encodes apolipoprotein E. LPG mainly affects Asian individuals, however occasional cases have also been described in Americans and Europeans." (PMID 34311745, 2021). "Lipoprotein glomerulopathy (LPG) is a rare hereditary renal disorder associated with abnormal lipid metabolism induced by variations in plasma apolipoprotein E (apoE)." (PMID 34513758, 2021).
lipoprotein glomerulopathy (continued). "Lipoprotein glomerulopathy (LPG) is a apolipoprotein E (ApoE)-related glomerular disease that was first reported as a glomerular disease associated with type III hyperlipidemia." (PMID 38769490, 2024). "Lipoprotein glomerulopathy (LPG) is a rare inherited disease caused by mutations in the APOE gene, encoding apolipoprotein E (apoE)." (PMID 34150810, 2021). "Lipoprotein glomerulopathy (LPG) is a rare kidney disease caused by APOE mutations." (PMID 32441489, 2020). "Lipoprotein glomerulopathy (LPG) is a rare inherited kidney disease, mainly caused by the APOE mutation." (PMID 23448537, 2013). "Mutations in apolipoprotein E (apoE) can result in histiocytic (apoE2 homozygote glomerulopathy) and non-histiocytic glomerulopathy (LPG), depending on the mutation types." (PMID 38673434, 2024). "This case may confirm the independent responsibility of ApoE2/2 and ApoE Toyonaka for ApoE2 homozygote glomerulopathy and MN-like EDD findings, respectively." (PMID 30542638, 2018). "Furthermore, lipoprotein glomerulopathy, a rare inherited renal disease characterized by proteinuria and progression to CKD, has a strong relation with mutations in the ApoE gene." (PMID 26790728, 2016). "Lipoprotein glomerulopathy [LPG, Online Mendelian Inheritance in Man (OMIM) #611771] is a rare genetic disorder mainly affecting people of Japanese and Chinese origin that is caused by a heterozygous mutation in the APOE gene on chromosome 19q13." (PMID 25352833, 2014). "Previously, it has been demonstrated that the apoE-/- mouse spontaneously develops lipoprotein glomerulopathy (LPG) at the age of 86 weeks and variations in the composition in dilated glomeruli lumens of apoE-/- mice compared to the apoE-Sendai mouse have been demonstrated." (PMID 20727187, 2010). "Lipoprotein glomerulopathy (LPG) is an autosomal dominant disease characterized by the histopathological feature of lipoprotein thrombi in the inner layer of glomerular capillaries and elevated serum apolipoprotein E (Apo E) levels." (PMID 36370330, 2023). "APOE-related disorders were recently summarized, mainly including APOE2 homozygote glomerulopathy (HLP), MN-like APOE disease, and LPG." (PMID 35602473, 2022). "Lipoprotein glomerulopathy (LPG) is a rare kidney disorder characterized by an abnormal plasma lipoprotein profile resembling HLP, glomerular lipoprotein thrombi, proteinuria, progressive kidney failure, and increased serum apoE concentration." (PMID 28660014, 2017).
cortical atrophy (26 papers, 2014 to 2025). "These inconsistencies in the relationship between years of education and cortical atrophy could be due to the lack of consideration of other contributing risk factors such as Aβ deposition, APOE ε4 carrier status, and tauopathy, which can all influence cortical atrophy." (PMID 37829142, 2023). "Second, the APOE ε2 genetic factor appears to exert a protective effect on the cerebral cortex, effectively slowing down cortical atrophy." (PMID 38894849, 2024). "In the APOE ε4ε4 group, higher global cortical atrophy score correlated with higher serum NfL (Rho = 0.78, p < 0.001) and higher plasma GFAP concentrations (Rho = 0.53, p = 0.024)." (PMID 38762725, 2024). "It is possible that our modest sample size precluded us from reaching statistically significant data on APOE genotype-related cortical atrophy due to the high degree of inter-animal variability in ventricle size within our colony." (PMID 37337279, 2023). "Therefore, they concluded APOE-e4 effects on cortical atrophy were limited to HM, and the dose effect of APOE-e4 on brain structures was largely delayed in time." (PMID 30852398, 2019). "However, more research including factors such as Aβ and tau protein retention, which affects cortical atrophy, is needed to better understand the possible effect of APOE ε4 genotype on the cortical atrophy in the subdivided trajectory of the MCI." (PMID 31551759, 2019). "Moreover, we also investigated whether APOE mRNA expression in the peripheral blood affected cognitive and severity scores through cortical atrophy." (PMID 40369256, 2025). "Another possibility is that patients who develop AD and have an APOE ε4 allele may have partly non-tau-dependent cortical atrophy, perhaps due to impaired neuronal repair in the presence of APOE ε4." (PMID 30086796, 2018). "No significant APOE group differences were seen in global cortical atrophy score (p = 0.52), medial temporal lobe atrophy score (p = 0.52), volumes of white matter hyperintensities (p = 0.36), entorhinal volume (p = 0.13) or parahippocampal volume (p = 0.12)." (PMID 38762725, 2024).
dyslipidaemia (26 papers, 2008 to 2025). "Although it may improve lipid transport and lower cholesterol levels in some cases, APOE ε2’s association with dyslipidaemia suggests a potential risk factor for cardiovascular disease under specific conditions." (PMID 40149595, 2025). "It has been hypothesized that the association between ApoE ε2 and risk of T2D is mediated by dyslipidaemia, although only minimally." (PMID 27540764, 2016). "This may reflect the impact of other parameters, for example, apolipoprotein E (apoE) genotype can affect the severity of dyslipidaemia, with the apoE 2/3 genotype being associated with an earlier onset and more pronounced form of dyslipidaemia than those with the apoE 3/3 genotype." (PMID 35920656, 2022). "In this study, we replicated the association seen with TC cholesterol and LDL, which suggests that APOE may contribute to the development of dyslipidaemia in patients with RA." (PMID 23613766, 2013). "It is also possible that dyslipidaemia and associated inflammation could contribute to the endothelial state in ApoE KO rats in vivo while these humoral factors were not present in the myograph." (PMID 32943715, 2020). "We suggest therefore that NO bioavailability might be reduced in pulmonary arteries from these ApoE KO rats on Western diet, possibly because of dyslipidaemia-induced oxidative stress, which may have been compensated by increased sensitivity of smooth muscle cells to NO." (PMID 32943715, 2020). "Briefly, APOE and LPA are components of LDL-C while ANGPTL3 and PCSK9 are known drug targets for dyslipidaemia treatment." (PMID 40689090, 2025).
glioma (26 papers, 2018 to 2026). A benign or malignant brain and spinal cord tumor that arises from glial cells (astrocytes, oligodendrocytes, ependymal cells). "The construction of our bioinformatics risk model identified ApoE as a protective factor linked to longer survival in glioma patients." (PMID 40662483, 2025). "Our results demonstrated that ApoE deficiency accelerates the growth of glioma and encourages the invasive behaviour of tumour cells into normal brain tissue." (PMID 40662483, 2025). "By delving into the CGGA database to analyse the correlations between ApoE and genes associated with glioma growth and resistance, we found that ApoE has a positive correlation with TSC2, a well‐recognised tumour suppressor gene." (PMID 40662483, 2025). "To elucidate the underlying mechanism of ApoE in glioma, we carried out transcriptome sequencing on the tumour tissue and the paired contralateral non‐tumour brain tissue obtained from mice with orthotopic tumorigenesis." (PMID 40662483, 2025). "Subsequently, we created an in situ tumorigenic mouse model and a subcutaneous tumorigenic mouse model with ApoE gene knockout to evaluate the functional impacts of ApoE deficiency in glioma." (PMID 40662483, 2025). "As a result, in the subsequent phase, we intend to carry out a thorough investigation into the role and underlying mechanism of ApoE within glioma." (PMID 40662483, 2025). "Additionally, we detected a reduction in the immune surveillance of glioma in the context of ApoE deficiency." (PMID 40662483, 2025). "One pilot study shows that the APOE ε4 allele may induce the cognitive decline of patients with glioma who have received radiotherapy ± chemotherapy." (PMID 36506554, 2022). "This study examined the spatial distribution of APOE in gliomas with two murine brain tumor models: ALTS1C1 and GL261." (PMID 40745073, 2026). "A previous study showed that APOE knockdown in U87 and U251 glioma cells reduced cell viability, migration, and invasion." (PMID 40745073, 2026). "These combined findings underscore the potential significance of ApoE in modulating the macrophage‐mediated immune response within the glioma microenvironment." (PMID 40662483, 2025). "When GL261 glioma cells were injected intracerebrally, ApoE−/− mice exhibited a significantly shorter survival time compared to WT mice (median survival: 18 days for ApoE−/− mice vs. 22 days for WT mice, p = 0.012)." (PMID 40662483, 2025). "To elucidate the relationship between ApoE and macrophages, we examined the single‐cell transcriptome sequencing data of glioma retrieved from the TISCH database." (PMID 40662483, 2025). "The findings demonstrated that, in comparison to wild‐type (WT) mice, glioma growth was notably more rapid in ApoE knockout mice." (PMID 40662483, 2025). "To elucidate the influence of ApoE on regulating the macrophage‐mediated immune response in the glioma microenvironment, we set up a non‐contact co‐culture system." (PMID 40662483, 2025). "exploited the property of APOE to effectively cross the blood-brain barrier in vitro to reveal APOE-mediated whole-body nano-delivery of granzyme B and CpG for the enhancement of glioma immunotherapy." (PMID 40292294, 2025). "The Apolipoprotein E knockout (ApoE−/−) mice model was employed to explore the role of ApoE in glioma." (PMID 40662483, 2025). "The UCNP were engineeredwith a peptide (apolipoprotein E, ApoE) which is known for good penetrationof the Blood Brain Barrier and good targeting of glioma cells." (PMID 39960048, 2025). "Macroscopic examination of the tumours revealed that the gliomas in ApoE−/− mice was significantly larger in size than those in WT mice." (PMID 40662483, 2025). "Our findings suggest that ApoE plays a crucial role in modulating glioma progression and immune surveillance, highlighting its potential as a therapeutic target." (PMID 40662483, 2025). "Utilising techniques such as flow cytometry, we delved into the role of ApoE in the glioma microenvironment." (PMID 40662483, 2025).
glioma (continued). "Analysis revealed that glioma patients with low ApoE expression had poorer overall survival, which was consistent with the findings from glioma patients in the TCGA dataset." (PMID 40662483, 2025). "We utilised immunohistochemistry to conduct a more comprehensive evaluation of ApoE expression in glioma patients." (PMID 40662483, 2025). "In this study, we explored the role of Apolipoprotein E (ApoE) in glioma using both bioinformatics and experimental methods." (PMID 40662483, 2025). "The results showed that ApoE expression was lower in high‐grade gliomas compared with fappedlow‐grade gliomas." (PMID 40662483, 2025). "Research on glioma has demonstrated that patients with high ApoE expression typically display longer survival times." (PMID 40662483, 2025). "After 8 h, there was a weak accumulation of free RNP in the glioma tissue of mice, while mice receiving non‐ApoE functionalized NC@RNP showed mild fluorescence." (PMID 38943253, 2024). "Microglia in mutant SETD2 (SETD2-mut)/IDH-WT GBM exhibit pro-inflammatory and proliferative phenotypes probably through stimulation of glioma-derived TGF-β1 expression via the apolipoprotein E (ApoE)-mediated NLRP1 inflammasome." (PMID 36555253, 2022). "Secondly, ANG-2 docking to CR17 revealed multiple and equally probable binding sites of ANG-2 on the complement repeat, closely resembling the avidity effect that characterized the ApoE internalization by glioma cells." (PMID 36235232, 2022). "In summary, we developed an ApoE-enriched PC-mediated brain-targeted drug delivery system for glioma treatment." (PMID 34963449, 2021). "The other one can benefit more glioma patients who have low ApoE expression or ApoE functional defects." (PMID 29956460, 2018). "Glioma patients who present with low ApoE expression tend to have a poorer overall survival rate." (PMID 40662483, 2025). "To investigate whether ApoE has an impact on the biological behaviour of glioma cells, we overexpressed ApoE in U251 and Ln229 cell lines." (PMID 40662483, 2025). "Recent investigations have indicated that the ApoE gene might play a crucial role in the development and survival of glioma." (PMID 40662483, 2025). "This negative modulation of immune function could potentially be part of the ApoE‐mediated mechanism that acts against glioma." (PMID 40662483, 2025). "Our research emphasises the pivotal function of ApoE expression in suppressing glioma growth." (PMID 40662483, 2025). "By zeroing in on the ApoE pathway, we could potentially enhance the immune responses to glioma, presenting a fresh avenue for efficacious treatment modalities." (PMID 40662483, 2025). "In ApoE‐knockout (ApoE−/−) mice, glioma tumours demonstrated an accelerated growth rate." (PMID 40662483, 2025). "In the glioma tumour tissues of ApoE−/− mice, the expression of ApoE was markedly decreased." (PMID 40662483, 2025). "We discuss the potential of the ApoE-enriched PC as a targeting strategy for brain delivery, which provides novel insights into glioma therapy and further improves the design of targeted drug delivery systems with high efficiency and enhanced safety for better clinical translation." (PMID 34963449, 2021). "From our MRM experiments using CSF we report that APOE could be a potential tumor progression marker in Meningioma and Glioma." (PMID 34055594, 2021).